PPARA (peroxisome proliferator activated receptor alpha)
Diseases named in the same sentence as PPARA in open-access papers (continued):
Sharing a sentence is not in itself a finding about the gene and the disease.
depression (36 papers, 2017 to 2026). "A mechanism underlying PPARα function in the expression of depression-like phenotypes may depend on BDNF expression." (PMID 35625650, 2022). "Therefore, hippocampal PPARα is implicated in both the pathogenesis of depression and antidepressant responses." (PMID 34211395, 2021). "Actually, besides neuroinflammation, the PPARα acts key roles in regulation of lipid metabolism, astrocyte also plays critical roles in development of depression via regulation of lipid metabolism." (PMID 40275171, 2025). "Nevertheless, recent studies have shown an emerging role of PPARα and its agonist in the pathophysiology of depressive disorders." (PMID 40943672, 2025). "It should be noticed that in addition to PPARα, PPARδ and PPARγ have been reported to correlate with depression as well." (PMID 40356991, 2025). "It is important to note that PPARG and PPARA are involved in lipid and glucose metabolism, while CHRM2 has been linked with depressive disorder." (PMID 37106802, 2023). "Modulation of dopamine neuronal firing in the ventral tegmental area likely contributes to PPARα effects in depression, anhedonia, and autism spectrum disorder (ASD)." (PMID 35625650, 2022). "Herein, we examine several mechanisms by which targeting PPARα regulates the pathophysiology of depression and anhedonia." (PMID 35625650, 2022). "Based on robust preclinical evidence and the initial results of clinical studies, future clinical trials should assess the efficacy of PPARα agonists in the treatment of mood and neurodevelopmental disorders, such as depression, schizophrenia, and ASD." (PMID 35625650, 2022). "Here, our study is the first comprehensive in vivo evidence suggesting that vortioxetine induces antidepressant effects in mice models of depression by significantly promoting the hippocampal PPARα expression." (PMID 34211395, 2021). "Here, our study provides a candidate, PPARα, as this protein not only correlates with BDNF biosynthesis and neuroplasticity but also is implicated in the pathogenesis of depression." (PMID 34211395, 2021). "There have been several studies regarding the role of hippocampal PPARα in depression neurobiology and antidepressant responses, including ours and others." (PMID 34211395, 2021). "Our study extends the knowledge of vortioxetine’s pharmacological effects and further highlights the role of PPARα in depression." (PMID 34211395, 2021). "In contrast, both knockdown and knockout of PPARα aggravated depression in mice." (PMID 40356991, 2025). "Peroxisome proliferator-activated receptor α (PPARα) has been demonstrated to play a role in the pathophysiology of depression, and several PPARα agonists including WY14643, fenofibrate, and gemfibrozil, have all been reported to possess antidepressant-like efficacy in rodents." (PMID 40356991, 2025). "Besides that, a previous study implicated that chronic stress significantly decreased the mRNA of PPARA in mice models, and The PPARA agonist WY14643 improved depressive-like behavior, which suggested PPARA is a therapeutic target for depression." (PMID 38195555, 2024). "A second hypothesis regarding dysfunctional neurocircuitry, and possible mechanisms that may contribute to the pathophysiology of depression, points to the role of hippocampal PPARα expression." (PMID 35625650, 2022). "Stimulating PPARα signaling induces potent behavioral effects and may offer a suitable treatment strategy to improve both symptoms of depression and anhedonia in patients." (PMID 35625650, 2022). "A primary mechanism by which PPARα may be involved in the regulation of major depression and anhedonia consists of the regulation of VTA dopamine neuronal firing." (PMID 35625650, 2022). "In contrast, genetic knockout and knockdown of PPARα aggravated depression in mice." (PMID 34211395, 2021).
depression (continued). "In addition to PPARα, there are a lot of other proteins that not only control BDNF biosynthesis and neuroplasticity but also are implicated in depression, such as salt-inducible kinase 2, glycogen synthase kinase 3β and mammalian target of rapamycin." (PMID 34211395, 2021). "Common variants in MTR, PPARA, ABCC3, CALML5, CACNB2 and PCDHB10 genes were associated with deficits in neurocognitive tests performance, whereas a variant in SLCO1B1 and EPHA5 genes was associated with anxiety and depression." (PMID 31181069, 2019). "Although the function of PPARα in the brain remained elusive for a long time, more and more studies indicate that PPARα is involved in physiological and pathological brain functions (e.g., in the sleep-wake cycle, depression, epilepsy, stroke and schizophrenia)." (PMID 32422896, 2020). "Functionally predicted germline common variants in MTR, PPARA, SLCO1B1, ABCC3, CALML5, CACNB2 and PCDHB10 genes were found to be significantly associated with deficits in neurocognitive tests performance, whereas a variant in EPHA5 gene was significantly associated with both anxiety and depression." (PMID 31181069, 2019). "Collectively, pharmacological inhibition of PPARα attenuated the protecting effects of vortioxetine against the CUMS and CSDS models of depression." (PMID 34211395, 2021). "In conclusion, we identified PPARα as a direct target of FMN, and our data firstly indicated that FMN ameliorates LPS-induced depression-like behaviors through rebalancing microglia M1/M2 polarization and inhibiting NLRP3 inflammasome, with involvement of activating PPARα-mediated autophagy." (PMID 40275171, 2025). "A structured literature search was conducted in PubMed/MEDLINE, Google Scholar, Scopus, Embase, and Web of Science databases using the following search terms: ‘depressive disorder’, ‘GLP-1 agonists’, ‘SGLT2 inhibitors’, ‘PPARα agonists’, ‘ARBs’, ‘ARNIs’, and ‘metabolic diseases’." (PMID 40943672, 2025). "To further validate the roles of PPARα in antidepressant effect of FMN, we treated PPARα antagonist GW6471 along with FMN (40 mg/kg, the more effective dose) in LPS-induced depressive mice, then carried out SPT, OFT, and TST to assess depression-like behaviors." (PMID 40275171, 2025). "However, the neurobiology of depression is very complex, involving not only BDNF but also a lot of other members regulated by CREB, such as mammalian target of rapamycin, vascular endothelial growth factor and peroxisome proliferator-activated receptor alpha." (PMID 33519490, 2020).
glioblastoma (36 papers, 2008 to 2025). The most malignant astrocytic tumor (WHO grade IV). "Dysregulation of lipid metabolism in glioblastoma is associated with several regulators, particularly PPARα, PPARγ, LXR, and SREBP-1." (PMID 40097417, 2025). "The MVA pathway plays a central role in glioblastoma survival; besides, its inhibition by PPARα antagonist is linked to cell death and tumor suppression." (PMID 29966227, 2018). "Recent evidence indicates that PPARα enhances glioblastoma (GBM) sensitivity to temozolomide (TMZ) and reverses acquired drug resistance through H3K18la inhibition." (PMID 40849305, 2025). "The complex tumor microenvironment of glioblastoma is influenced by PPARα, which affects tumor cell proliferation." (PMID 40097417, 2025). "Although these findings suggest that PPARα has a detrimental effect on promoting tumor growth, several reports indicate that PPARα can also inhibit glioblastoma growth." (PMID 40097417, 2025). "The use of GW6471 to antagonize PPARα activity was found to improve glucose and lipid tumor metabolism, thereby reducing glioblastoma proliferation." (PMID 37251321, 2023). "Massive PPARα activation is related to tumor growth progression in different cancers, including glioblastoma, renal cancer, and triple-negative breast cancer." (PMID 33525605, 2021). "Through ChIP-PCR analysis, it was shown that after knockdown of the expression of HOTAIR in glioblastoma, the binding of histone H3K27me3 in the promoter region of the PPARα gene was significantly reduced." (PMID 34082742, 2021). "We have recently shown that PPARα gene and protein expression is increased in glioblastoma and has independent clinical prognostic significance in multivariate analyses." (PMID 30565681, 2019). "Recently, we demonstrated decreased tumor proliferation with an alteration of glucose and lipid tumor metabolism, antagonizing PPARα by synthetic ligand (GW6471) in glioblastoma stem cells (GSCs)." (PMID 29966227, 2018). "In our study, we confirmed that FF inhibits glioblastoma glycolysis in a dose-related manner depending on PPARα activation." (PMID 26172294, 2015). "Fenofibrate is an FDA approved PPARα agonist that has previously been shown to block the proliferation and migration of glioblastoma." (PMID 24705102, 2013). "The regulation of lipid metabolism by both PPARα and PPARγ plays a crucial role in shaping the biological behavior of glioblastoma, which is involved in lipid homeostasis and cellular signaling, and presents promising avenues for therapeutic intervention in glioblastoma." (PMID 40097417, 2025). "Glioblastoma stem cells are metabolically reprogrammed under hypoxic conditions by upregulating glucose transporters, glucose uptake, and glycogen and lipid storage, in a process that results from the activation of PPARα by hypoxia-inducible factor-1 (HIF-1)." (PMID 37251321, 2023). "We have recently shown in glioblastoma stem cells and glioblastoma primary cells that PPARα inhibition by specific antagonists (GW6471 and AA452) determined growth arrest, decreased expression of the enzymes of the mevalonate pathway, and reduced levels of cholesterol and cholesterol esters." (PMID 33525605, 2021). "Although activation of PPARα may explain some of the observed anticancer effects, glioblastoma cells treated with PPARα siRNA retain sensitivity to FF, indicating a PPARα-independent mechanism of FF anticancer action." (PMID 31745126, 2019). "In addition, we demonstrated that glioblastoma and GSCs in hypoxic condition show higher levels of PPARα compared with the normoxic condition, while PPARγ levels are downregulated under hypoxia." (PMID 29966227, 2018). "Notably, the fluorescence intensity for PPARα in HNPGL cell lines was comparable to what we have previously observed in glioblastoma, a tumor overexpressing PPARα whose viability is also affected by a PPARα antagonist." (PMID 28594934, 2017). "In glioblastoma cells, the interaction of PPARα and RelA only appeared in the cytoplasm." (PMID 26172294, 2015).
glioblastoma (continued). "We found that FF inhibited glycolysis in a PPARα-dependent manner in glioblastoma cells." (PMID 26172294, 2015). "The results indicated that the action of FF on glioblastoma cell glycolysis is PPARα dependent." (PMID 26172294, 2015). "This may also suggest that Glioblastoma cells require exogenous stimulation to activate/translocate PPARα to the nucleus." (PMID 20569465, 2010). "Targeting PPARα in GSC populations may therefore have translational potential as a novel adjuvant therapeutic approach to abrogate the contribution of GSC to the poor overall clinical survival for glioblastoma patients." (PMID 30565681, 2019). "The PPARα antagonist AA452 downregulates the expression of c-Myc, cyclin D1, p-FAK, COX2, and pERK1/2 in glioblastoma primary cells, blocks cell proliferation, and increases sensitivity to radiotherapy." (PMID 40097417, 2025). "Another study suggested that the expression of PPARα protein and the PPARA gene is increased in glioblastoma samples, and glioblastoma patients with high PPARA expression had a significant increase in overall survival in the TCGA dataset." (PMID 40097417, 2025). "GSEA of concordant genes confirmed epigenetic regulation of pathways known to be contributing to glioblastoma pathogenesis such as transcription factors RUNX, SMADs and PPARA, neddylation of protein, homeostasis disorder including Basigin and Kallikrein/kinin complex." (PMID 39915814, 2025). "In contrast to control cells with intact PPARα expression, knockdown cells did not form tumors in vivo, suggesting PPARα inhibition as a potential target for the inhibition of glioblastoma growth." (PMID 35954274, 2022). "PPARα‐expressing control GSC xenografts formed invasive histological phenocopies of human glioblastoma, whereas PPARα KD GSC xenografts failed to establish viable intracranial tumours." (PMID 30565681, 2019). "Furthermore, NTRK2 was associated with peroxisome proliferator–activated receptor α (PPARα), which was overexpressed and correlated with a good prognosis in IDH wild-type primary glioblastoma." (PMID 30991699, 2019). "In this respect our preliminary studies (not shown) demonstrate elevated levels of PPARα in multiple Glioblastoma clinical samples." (PMID 20569465, 2010). "We hypothesise that high PPARA exerts an inhibitory effect on glioblastoma glycolysis 77, an effect not seen in the GSC population." (PMID 30565681, 2019).
ischemia (36 papers, 2011 to 2025). A hypoperfusion of the BLOOD through an organ or tissue caused by a PATHOLOGIC CONSTRICTION or obstruction of its BLOOD VESSELS, or an absence of BLOOD CIRCULATION. "The positive enrichment scores across these pathways indicate their upregulation in ischemic brain tissue from the loss of PPARα and point to a potential protective or modulatory effect of PPARα against ischemia-induced pathological changes in gene expression." (PMID 40362325, 2025). "Although the loss of SIRT1/SIRT3 led to a compromised PGC‐1α/PPARα‐mediated transcriptional control of fatty acid oxidation in response to acute ischemia and I/R, their crosstalk in mitochondria plays a more important role in the aging heart during acute ischemia." (PMID 37537789, 2023). "Regarding FA metabolism, there was a notable increase in PGC-1α and PPARα gene expression 90 min after ischemia onset compared to baseline levels." (PMID 41009389, 2025). "THC can increase the expression and activity of PPARα, improving endothelial cell function and protecting them against ischemia and high intraventricular pressure." (PMID 38978789, 2024). "Previous studies have reported that PPARα’s neuroprotective effects in ischemic stroke are related to the inhibition of ischemia-induced oxidative stress and inflammation." (PMID 37111378, 2023). "This study provides the first evidence that a novel selective PPARα agonist, pemafibrate promotes endothelial cell function and revascularization under conditions of ischemia." (PMID 32584895, 2020). "We investigated the protective effect of PPARα activation against cardiac ischemia-reperfusion injury in terms of the expression of uncoupling protein (UCP)." (PMID 26770648, 2016). "Peroxisome proliferator-activated receptor alpha (PPARα) ligands have been shown to modulate recovery after brain insults such as ischemia and irradiation by enhancing neurogenesis." (PMID 27013951, 2016). "Beneficial effects on infarct size and cardiac performance were also found in rats and mice with in vivo ischemia reperfusion and PPARα agonist treatment." (PMID 26713088, 2015). "In isolated perfused rat hearts with 30 minutes of ischemia followed by 2 hours of reperfusion, the PPARα agonist WY14643 or clofibrate improved cardiac contractile function and decreased infarct size." (PMID 26713088, 2015). "In the nervous system, activated PPARα appears to be involved in neuronal differentiation, inflammation, and autoimmune modulation, and also protects nerves against ischemia." (PMID 24392081, 2014). "In obstructive nephropathy (UUO models), BBR predominantly addresses ischemia-induced tubular metabolic dysfunction by restoring FAO via AMPK/PPARα activation, while selectively inducing ferroptosis in ECM-producing myofibroblasts through Fe2+/MDA/ROS reduction." (PMID 40567371, 2025). "Briefly, these data first proposed that OEA-mediated PPARα activation could be an effective therapy against hepatic ischemia/reperfusion injury." (PMID 35356086, 2022). "Also in vivo studies report increased infarct size and decreased cardiac function after ischemia followed by 24 hours of reperfusion with PPARα agonist treatment or in mice with cardiomyocyte-specific overexpression of PPARα." (PMID 26713088, 2015). "In relation to PPARα, this receptor has been reported to mediate the neuroprotective effect of non-cannabinoid AEs in cognitive impairment, inflammation, neurodegeneration and neuronal damage after ischemia." (PMID 26578900, 2015). "However, OEA keeps ischemia-induced microglia in the M2 state through PPARα." (PMID 37111378, 2023). "On day 7, following ischemia, the mRNA levels of HIF-1α and PPARα returned to the levels observed in the control group." (PMID 38575595, 2024). "Our study highlights PPARα as an attractive drug target for ischemic stroke due to its transcriptional regulation of inflammation-, apoptosis-, and EMT-related genes in brain tissue following ischemia." (PMID 40362325, 2025).
ischemia (continued). "Additionally, our data also showed that PPARα deletion enhances OGD-induced neuronal death, which further confirms the beneficial role of PPARα signaling in neuroprotection after ischemia." (PMID 37111378, 2023). "In contrast, mice with cardiac overexpression of PPARα showed highest FAO, lowest glucose oxidation rates as well as worst recovery of cardiac power, indicating a detrimental effect of chronic PPARα activation on cardiac recovery after ischemia." (PMID 33322384, 2020). "Based on the regulatory role of PPARα in the expression of UCP, we hypothesized that the mechanism of cardioprotective effect of PPARα against ischemia-reperfusion injury could involve increased expression of UCP, particularly UCP3, and resultant attenuation of ROS generation." (PMID 26770648, 2016).